FGF21 (fibroblast growth factor 21)
Diseases named in the same sentence as FGF21 in open-access papers (continued):
Sharing a sentence is not in itself a finding about the gene and the disease.
heart failure (continued). "Our impetus for this study is based on the hypothesis that βOHB and FGF21 act as signaling molecules regulating the cardiac metabolism under nutrient stress conditions including heart failure." (PMID 35513524, 2022). "However, exploration of molecular basis and targeting potential of FGF21 resistance in heart is needed for therapeutic implications of heart failure." (PMID 35983184, 2022). "Clinical studies on FGF21 and heart failure in human subjects are limited." (PMID 27650781, 2016). "Interestingly, it has been shown that the human heart is also a source of FGF21, increasing in patients suffering from heart failure." (PMID 26379627, 2015). "However, little is known about the role of FGF21 in heart failure (HF)." (PMID 36028609, 2023). "Thus, FGF21 can exert cardioprotective effects through multiple mechanisms, thereby improving structural remodeling and reducing the occurrence of heart failure, and is promising as a potential cytokine for the treatment of heart failure." (PMID 36778154, 2023). "Promising novel biomarkers that showed good performance in detecting diastolic dysfunction or heart failure in diabetic patients include galectin-3, ST2, FGF-21, IGFBP-7, GDF-15, and TGF-β." (PMID 39335666, 2024). "There are some promising novel biomarkers, such as galectin-3, ST2, FGF-21, IGFBP-7, GDF-15, and TGF-β, that provide good specificity in diagnosing diastolic dysfunction or overt heart failure in diabetic patients." (PMID 39335666, 2024). "In this study, we observed significantly elevated serum FGF21, NT-proBNP and troponin I levels in STEMI patients after emergency PCI who developed heart failure." (PMID 36778154, 2023). "According to the ROC curve analysis, the AUC of NT-proBNP to predict the occurrence of heart failure during hospitalization in STEMI patients was 0.929 (95% CI [0.901–0.957]), while the AUC of FGF21 was 0.816 (95% CI [0.770–0.863])." (PMID 36778154, 2023). "Our results demonstrated that circulating FGF21 was related to BNP, LVEF, and LVEDD in heart failure subjects." (PMID 35069790, 2022). "Both FGF21 and NT-pro-BNP concentrations had good prognostic value to the 1-year adverse cardiac events in patients with preserved ejection fraction heart failure." (PMID 27650781, 2016). "Serum FGF21 levels were significantly higher in the STEMI group with heart failure than in the group without heart failure (249.95 ± 25.52 vs. 209.98 ± 36.35, P < 0.001)." (PMID 36778154, 2023). "The change of FGF21 concentration was not shown, especially during the progression of heart failure." (PMID 35069790, 2022). "Therefore, FGF21 and BNP have a certain prognostic value for 1-year adverse cardiac events in patients with heart failure with a reduced ejection fraction." (PMID 35069790, 2022). "Compared to patients without heart failure, those with HFpEF had significantly higher levels of FGF21 (mean 146.79 pg/mL vs. 298.98 pg/mL)." (PMID 34573919, 2021). "Although elevated circulating FGF21 levels have been observed in RA and associated with altered body composition, reduced physical function, and increased inflammatory cytokines, its prognostic value for LVDD and heart failure in RA has not been investigated." (PMID 41464745, 2025). "However, there are no studies correlating serum FGF21 levels with heart failure after AMI during hospitalization in ST segment elevation myocardial infarction (STEMI) patients treated with emergency percutaneous coronary intervention (PCI)." (PMID 36778154, 2023). "Data about the change of FGF21 concentration at the time of heart failure progression were absent." (PMID 27650781, 2016). "Therefore, FGF21 may be a potential biomarker for the development of heart failure during hospitalization in STEMI patients after emergency PCI, and it has predictive value for the development of heart failure." (PMID 36778154, 2023).
heart failure (continued). "The LDL-C, troponin I, NT-proBNP, FGF21 levels, LAD, LVEDD, LVESD, and LVESV were higher in the heart failure group than in the no heart failure group, while the HDL-C levels and LVEF were lower than in the no heart failure group (P < 0.05)." (PMID 36778154, 2023).
hyperlipidemia (43 papers, 2011 to 2025). "Through a genome-wide association study (GWAS), circulating FGF21 has been identified as possessing a strong causal effect on improved hyperlipidemia and liver function biomarkers including fibrosis." (PMID 36618930, 2022). "Adenoviral knockdown of hepatic Fgf21 in mice fed KD caused reduced blood ketone levels, fatty liver, and lipemia, suggesting that FGF21 is required for hepatic ketogenesis and triglyceride clearance in mice fed KD." (PMID 21331285, 2011). "Taken together, the data suggest that BAT activation might be a tool for the alleviation of hyperlipidemia by DCA in association with FGF21 induction." (PMID 31570705, 2019). "Only patients with developed FPLD2 had elevated HbA1c, hyperlipidemia, and FGF21, indicating that systemic metabolic dysfunction emerges later with severe adipose loss." (PMID 41217838, 2025). "In diet-induced obese mice, we found that FGF21/sTGFBR2 had greater improvements on insulin sensitivity and hyperlipidemia at warmer temperatures (i.e., 26°C and 30°C)." (PMID 40663389, 2025). "Increased hyperlipidemia-specific genes further increased stress-induced myokine FGF21 which was indicative of imbalanced muscle cell functioning." (PMID 36829889, 2023). "Surprisingly, APC has also been found to reduce the transcription of SREBPs and their target genes, and to increase plasma FGF21 levels, which leads to the improvement of hyperlipidemia in these animals." (PMID 35017472, 2022). "Our results indicate that hyperlipidemia is also accompanied by increased Fgf21 expression in adipose tissues, especially in female mice." (PMID 33919597, 2021). "Fish oil supplements (4 g) for 3 months improved lipid and glucose levels, liver function and the circulating biomarkers FGF21 and CK18 fragment, and performed anti-inflammation functions in patients with NAFLD associated with hyperlipidemia." (PMID 26226139, 2015). "In addition, the patients in the high FGF21 group also had lower rates of hyperlipidemia, current smoker, and statin medication, as well as lower left ventricular ejection fraction (LVEF) compared with those who had the low FGF21 group." (PMID 36180826, 2022). "Consistent with the metabolic benefits observed upon pharmacological administration of FGF21 in preclinical species, a recent clinical trial demonstrated robust effects of a stabilized FGF21 analog, LY2405319, in reducing hyperlipidemia and promoting body weight loss in obese T2D subjects." (PMID 25790234, 2015). "We conducted a double-blind, randomized clinical trial to assess the effects of fish oil on lipid, glucose and other CVD risk factors, liver enzymes, NAFLD biomarkers such as FGF21 and CK18 fragment M30 (CK18-M30), and some inflammatory cytokines in adults with NAFLD associated with hyperlipidemia." (PMID 26226139, 2015). "Mice with the fgf21 gene deletion (FGF21-KO, FGF21-knockout) do not show PPARγ effects, such as reduction of fat and lipemia, improvement of tissue insulin sensitivity, and increase of lipogenesis." (PMID 30927227, 2019). "FGF21 does not improve hyperlipidemia or hyperinsulinemia of lipodystrophic mice housed at 22°C." (PMID 40663389, 2025). "However, FGF21 supplement had no impact on blood glucose level and hyperlipidemia, suggesting that FGF21-induced cardiac protection against DIO is not the consequence of regulation of global glucose and lipid metabolism." (PMID 29445083, 2018).
Glucose intolerance (40 papers, 2013 to 2025). Glucose intolerance (GI) can be defined as dysglycemia that comprises both prediabetes and diabetes. "It is worth noting that FGF21 KO by itself causes glucose intolerance and higher liver triglyceride content." (PMID 34314389, 2021). "In our previous research, we found that time-restricted feeding rescues female mice from body weight gain and glucose intolerance as well as from ovarian follicle loss and dysfunction of estrus cyclicity induced by a high-fat diet via liver FGF21." (PMID 33820556, 2021). "The findings indicated that upregulation of circulating FGF21 was linked with adiposity or glucose intolerance in patients with thyroid cancer, whereas previous studies focused on the role of FGF21 in metabolic diseases." (PMID 31408968, 2019). "Our previous report demonstrated that BAFF deficiency prevents mice from HF diet-induced glucose intolerance at least in part by potentiating brown adipose tissue function, particularly through enhancement of FGF21 expression and leptin action." (PMID 27814392, 2016). "FGF-21 deficiency, however, might have contributed to the observed weight gain and glucose intolerance in Gprc6aLiver-cko mice." (PMID 32350388, 2020). "EVs released into the serum from brown adipocytes contain a significant level of miR-99b, which targets FGF21 in the liver, thereby contributing to metabolic dysfunctions such as glucose intolerance in obesity." (PMID 37566042, 2023). "Together, our results demonstrate that the main phytochemicals from cocoa by-products, especially protocatechuic acid, can trigger FGF21 signaling and attenuate inflammation, oxidative stress, lipid accumulation, and glucose intolerance in HepG2 hepatocytes." (PMID 35052640, 2022). "Fgf21 produces FGF21, a hormone that is known to regulate lipid accumulation and glucose intolerance." (PMID 36140300, 2022). "Knockout mouse models for FGF15, the mouse ortholog of FGF19, and for FGF21 develop glucose intolerance and insulin resistance." (PMID 30374109, 2018). "In order to explain the occurrence of glucose intolerance in pHF Wistar rats, plasma levels of adiponectin and FGF21, two modulators of insulin sensitivity, were determined." (PMID 27618559, 2016). "These mice, when fed the low carbohydrate diet, exhibited glucose intolerance, decreased serum levels of FGF21 and also decreased expression of hepatic SCD1." (PMID 25170869, 2014). "As mice fed KD for 6 days already exhibited impaired insulin sensitivity, resulting in glucose intolerance, we examined blood glucose, insulin, and glucagon levels in wild-type and Fgf21 knockout mice fed NC or KD for 6 days." (PMID 23874946, 2013). "Transplantation of BAT to the ADicerKO mice effectively restored the amount of circulating exosomal miRNAs and mitigated glucose intolerance with the level of fibroblast growth factor 21 (FGF21), a hormone that can regulate liver metabolism, remarkably reducing its circulation." (PMID 34703651, 2021). "PPARα activation by bilirubin in obese mice with glucose intolerance leads to a decrease in fasting blood glucose, as well increase in lean body mass and an increased presence of FGF21 (fibroblast growth factor 21)." (PMID 35204062, 2022). "BAT-derived FGF21 is also dispensable for the improvements in glucose homeostasis and insulin sensitivity in OPA1 BAT KO mice, as HFD-induced glucose intolerance was attenuated in DKO mice, and fasting glucose levels were reduced." (PMID 33944779, 2021). "This contrasts with previous studies that reported glucose intolerance in Fgf21 KO mice on a chow diet, but not on a high‐fat diet." (PMID 40787810, 2025). "Together, these data suggest that FGF21 and GDF15 act synergistically to improve glucose homeostasis and insulin sensitivity in OPA1 BKO male mice, with their combined absence resulting in glucose intolerance and prevention of improvement in insulin sensitivity." (PMID 40897647, 2025).
Glucose intolerance (continued). "Mice lacking hepatocyte NAMPT exhibit defective FGF21 activation and thermal regulation during fasting, and are sensitized to diet-induced glucose intolerance." (PMID 35228549, 2022). "Our data demonstrated that an LPD-induced increase in FGF21 may be related to overexpression of UCP1 in BAT, resulting in improvement of glucose intolerance in WFRs." (PMID 29507597, 2018). "Moreover, mice lacking FGF21 gain weight, have an increased fat mass and develop glucose intolerance." (PMID 28534852, 2017). "Median of leptin and FGF21, but not of FGF23, were statistically higher in patients with DMT2 and fasting glucose intolerance." (PMID 32570721, 2020).
Mitochondrial myopathy (40 papers, 2013 to 2025). "In mitochondrial myopathies, elevated serum FGF21 from skeletal muscle is now recognized as a diagnostic biomarker." (PMID 40788112, 2025). "Although plasma FGF21 levels have been described as biomarkers of metabolic disorders or mitochondrial myopathies, its release from muscle has been associated with improvements in metabolic function." (PMID 36909316, 2023). "Five studies that compared the performance of GDF-15 and FGF-21 as diagnostic biomarkers for mitochondrial myopathy all showed higher sensitivity of the former, three also allocated higher specificity to GDF-15." (PMID 36361969, 2022). "The main difference between them is that the predictive value of FGF-21 seems to be restricted to patients with mitochondrial myopathies, as well as to those carrying point mutations within mtDNA and in mtDNA maintenance-related genes." (PMID 34203775, 2021). "There is also a positive association between mitochondrial myopathy and increased FGF-21 levels in the sera of mice." (PMID 24078096, 2013). "Since 2011, FGF21 has been repeatedly reported as a potential biomarker for mitochondrial myopathies and PMDs caused by mechanisms primarily or secondarily affecting mitochondrial translation, such as direct mutation of a translation machinery and mtDNA deletion." (PMID 35498801, 2022). "If muscle FGF21 were the only source for increased plasma FGF21, however, higher levels might be expected to associate with more advanced disease (i.e. more muscle atrophy) as has been observed with mitochondrial myopathies." (PMID 40788112, 2025). "Deletion of FGF21 in OPA1‐deficient mice, a model of mitochondrial myopathy, resulted in partial attenuation of muscle wasting and prolonged survival." (PMID 39976232, 2025). "Correspondingly, elevated serum FGF21 has been detected in humans with mitochondrial respiratory chain defects in muscle, suggesting its potential utility as a biomarker for diagnosing mitochondrial myopathies." (PMID 41234361, 2025). "Nevertheless, it is worth noting that FGF21 is also considered a marker of mitochondrial myopathy and aging." (PMID 38902808, 2024). "FGF21 expression is significantly increased in the muscles of mice with mitochondrial myopathies, where its levels are directly related to the presence of cytochrome oxidase negative fibres, a marker associated with the severity of the disease." (PMID 39156689, 2024). "FGF21 is highly expressed in muscle tissue during periods of fasting, metabolic disorders, and mitochondrial myopathy." (PMID 38902808, 2024). "In skeletal muscle, FGF21 is synthesised under conditions of stress such as mitochondrial myopathies." (PMID 36028609, 2023). "In mitochondrial myopathies, FGF21 is induced and secreted from muscle for starvation-induced lipolysis, and this stress response is observed in both humans and mice." (PMID 35906243, 2022). "Such a strategy has been proposed for mitochondrial myopathies, where its combination with the other well-studied biomarker and regulator of energy metabolism fibroblast growth factor-21 (FGF-21) is proposed." (PMID 36361969, 2022). "We found that loss of Rrm2b in the myofibers upregulated the expression of Fgf21, which is a local and systemic messenger in mice and humans with mitochondrial myopathy through autocrine and paracrine mechanisms." (PMID 35906243, 2022). "FGF21 was first reported as a potential biomarker in PMDs, since its serum concentration was found sensitive and specific for mitochondrial myopathies." (PMID 35498801, 2022). "For example, FGF21 is elevated in obese individuals and those with T2D, and in mitochondrial myopathy and metabolic stress conditions." (PMID 34177798, 2021). "Fibroblast growth factor 21 is induced in and secreted from skeletal muscle in mitochondrial myopathies and insults of various stresses in skeletal muscle." (PMID 33762965, 2021).